MUSTN1 (musculoskeletal, embryonic nuclear protein 1)
Description:
Required for chondrocyte development and proliferation. Plays a role in myoblast differentiation and fusion. Modulates skeletal muscle extracellular matrix composition. Plays a role in skeletal muscle function. Plays a role in glucose homeostasis.
Synonyms: Mustang
Tractability: Antibody: UniProt places it where antibodies can reach, with medium confidence; its Gene Ontology location is reachable by antibodies, with medium confidence.
Gene: Protein-coding gene on chromosome 3 (52,833,114 to 52,835,019, reverse strand). Ensembl gene ENSG00000272573.
Subcellular location: Nucleus; Cytoplasm; Secreted, extracellular space
Gene Ontology:
Biological process: glucose homeostasis; positive regulation of myoblast differentiation; chondrocyte differentiation; chondrocyte proliferation; embryonic limb morphogenesis; tissue regeneration
Cellular component: cytoplasm; nucleus; extracellular region; nucleoplasm
Genetic constraint (gnomAD): Loss-of-function variants: 14 observed, 11.73 expected, observed/expected ratio (o/e) 1.19, 90% interval 0.78 to 1.78. The upper end of that interval is the gene's LOEUF score, 1.78, which puts it in group 6 of 6, group 1 being the genes least tolerant of losing a copy. Missense variants: 111 observed, 104.19 expected, observed/expected ratio (o/e) 1.07, 90% interval 0.91 to 1.25. Synonymous variants: 42 observed, 40.71 expected, observed/expected ratio (o/e) 1.03, 90% interval 0.81 to 1.33.
Homologues: Orthologues: rabbit MUSTN1 (96% identical), chimpanzee MUSTN1 (94% identical), guinea pig MUSTN1 (85% identical), rat Mustn1 (85% identical), dog MUSTN1 (84% identical), mouse Mustn1 (84% identical), tropical clawed frog mustn1 (67% identical), zebrafish mustn1b (60% identical), zebrafish mustn1a (48% identical). Paralogues in human: STIMATE (13% identical).
Diseases named in the same sentence as MUSTN1 in open-access papers:
MUSTN1 is named in the same sentence as 21 diseases in open-access papers, as found by Europe PMC text mining. Sharing a sentence is not in itself a finding about the gene and the disease. The quoted sentences say what the papers report.
diabetes (2 papers, 2017 to 2024). "The obesity SNP rs2710323, together with two diabetes SNPs, rs2590838 (r2, 0.78) and rs1108842 (r2, 0.8), are located in loci that regulate genes (TMEM110, MUSTN1, ITIH4, NEK4, GNL3, PBRM1, and NT5DC2) within a 300 kb genomic region on chromosome 3." (PMID 29081791, 2017).
muscular dystrophies (2 papers, 2024). "Clinically, Mustn1 expression is potentially linked to muscle-wasting conditions such as muscular dystrophies." (PMID 39062608, 2024). "Understanding the molecular mechanisms and interactions of Mustn1 with other proteins and pathways implicated in muscular dystrophies can reveal new insights into the pathological mechanisms of these conditions." (PMID 39062608, 2024). "Understanding the molecular mechanisms and interactions of Mustn1 with other proteins and pathways implicated in muscular dystrophies will reveal new insights into the pathological mechanisms of these conditions." (PMID 39062608, 2024). "Since muscular dystrophies are characterized by the progressive weakening and loss of muscle mass, it is conceivable that they may be influenced by the expression and function of Mustn1, which is known to be associated with muscle regeneration." (PMID 39062608, 2024). "As such, disruption or alteration in Mustn1 expression or function could potentially exacerbate the symptoms of muscular dystrophies or contribute to the onset of these conditions." (PMID 39062608, 2024). "Although there is no clear known connection, the relationship between Mustn1 and muscular dystrophies is plausible due to the protein’s significant role in muscle development and repair." (PMID 39062608, 2024). "A more modest increase in Mustn1 expression could also be seen in EDL and psoas muscle (but not soleus) in a mouse model of muscular dystrophy." (PMID 38458566, 2024).
Obesity (2 papers, 2017 to 2025). Accumulation of substantial excess body fat. "The results revealed a new biological function in fat deposition for MUSTN1 and provided new ideas and targets for improving the economic benefits of animal husbandry and preventing obesity-related diseases." (PMID 40239869, 2025). "This study reveals a positive regulator for fat development, which suggests a novel approach for studying obesity and animal genetic improvement through the modulation of MUSTN1 expression." (PMID 40239869, 2025). "To better understand MUSTN1 function in vivo, we subjected the mice to a HFD for 3 months to induce obesity." (PMID 40239869, 2025). "Our work revealed the critical role of MUSTN1 in regulating adipogenesis by interacting with FABP3 and activating the PI3K/AKT signaling pathway, providing a theoretical foundation and a potential molecular target for improving animal performance and treating obesity-related diseases." (PMID 40239869, 2025).
Hepatic steatosis (1 paper, 2025). Steatosis is a term used to denote lipid accumulation within hepatocytes. "Therefore, HFD mice exhibited ectopic adipose transfer and hepatic steatosis, and MUSTN1-KO mice alleviated the phenomenon of hepatic adipose deposition caused by an HFD." (PMID 40239869, 2025).
Insulin resistance (1 paper, 2025). Increased resistance towards insulin, that is, diminished effectiveness of insulin in reducing blood glucose levels. "We found a reduced adipokine content in MUSTN1-KO mice compared with WT mice, which also explains the phenotype of reduced fat mass and improved insulin resistance from another perspective." (PMID 40239869, 2025). "We observed that MUSTN1-KO enhanced glucose tolerance and insulin sensitivity in mice fed an HFD, protecting against HFD-induced insulin resistance." (PMID 40239869, 2025).
lipidosis (1 paper, 2025). "Our research provides a basis for understanding the correlation between MUSTN1 and the PI3K/AKT signaling pathway in the regulation of lipidosis." (PMID 40239869, 2025).
myositis (1 paper, 2025). "The most significantly reduced protein was MUSTN1 (Musculoskeletal embryonic nuclear protein 1, also known as Mustang), which we recently showed to be induced by muscle injury and highly expressed in untrained muscle from subjects with muscle dystrophy by myositis." (PMID 41114770, 2025).
osteoarthritis (1 paper, 2018). A noninflammatory degenerative joint disease occurring chiefly in older persons, characterized by degeneration of the articular cartilage, hypertrophy of bone at the margins and changes in the synovial membrane. "The plausibility that Mustn1 is linked to osteoarthritis is not surprising as Mustn1 is known to be expressed in adult articular cartilage, especially by proliferating chondrocytes in the superficial/tangential zone (unpublished observations)." (PMID 29329193, 2018). "This led the authors to suggest that the arcOGEN study has provided very novel insights into the etiology of osteoarthritis by the fact that the majority of the genes identified, including Mustn1, have not previously been suggested to have a role in osteoarthritis." (PMID 29329193, 2018).
Osteopenia (1 paper, 2024). Osteopenia is a term to define bone density that is not normal but also not as low as osteoporosis. "For example, examination of Mustn1 expression during osteopenia and osteoporosis may reveal insights into whether its expression can be regulated by mechanical loading/unloading." (PMID 39062608, 2024).
peripheral artery disease (1 paper, 2024). "With this in mind, we measured Mustn1 expression in tibialis anterior after femoral artery ligation (FAL), which is a well-established model of peripheral artery disease." (PMID 38458566, 2024).
cancer (2 papers, 2014 to 2025). A tumor composed of atypical neoplastic, often pleomorphic cells that invade other tissues. "Using machine learning algorithms, including RF, SVM, GBM (XGBoost), and DT, the genes CDH3, DKC1, ESM1, MUSTN1, RCC2, TMT1A, and VEGFD were selected as key features from the tissue dataset to best discriminate between cancer and control samples and were used to design the predictive model." (PMID 40425785, 2025).
MUSTN1 also shares sentences with these, for which no sentence is quoted: breast carcinoma (1 paper); Cryptozoospermia (1); infection (1); ischemia (1); lung carcinoma (1); metabolic disease (1); myopathies (1); osteoporosis (1); sarcopenia (1); tumor (1).